RPL4P4 (ribosomal protein L4 pseudogene 4)
Synonyms: RPL4_2_444
Gene: Processed pseudogene on chromosome 3 (185,417,495 to 185,418,778, reverse strand). Ensembl gene ENSG00000229638.
Diseases named in the same sentence as RPL4P4 in open-access papers:
RPL4P4 is named in the same sentence as 1 disease in open-access papers, as found by Europe PMC text mining. Sharing a sentence is not in itself a finding about the gene and the disease. The quoted sentences say what the papers report.
glioma (2 papers, 2023 to 2025). A benign or malignant brain and spinal cord tumor that arises from glial cells (astrocytes, oligodendrocytes, ependymal cells). "However, other ribosomal pseudogenes, such as RPL4P4, have been reported as prognostic markers and may act as competitive endogenous RNAs (ceRNAs), influencing gene expression regulation in gliomas." (PMID 40725410, 2025).